FOXD4L3 (forkhead box D4 like 3)
Synonyms: OTTHUMG00000019959; FOXD6
Tractability: No criterion of Open Targets' tractability assessment is met for any kind of drug.
Gene: Protein-coding gene on chromosome 9 (68,302,867 to 68,305,084, forward strand). Ensembl gene ENSG00000187559.
Subcellular location: Nucleus
Subcellular location (Human Protein Atlas): Nucleoplasm
Gene Ontology:
Molecular function: protein binding; DNA-binding transcription factor activity, RNA polymerase II-specific; RNA polymerase II cis-regulatory region sequence-specific DNA binding; DNA-binding transcription factor activity; sequence-specific DNA binding
Biological process: anatomical structure morphogenesis; cell differentiation; regulation of transcription by RNA polymerase II; regulation of DNA-templated transcription
Cellular component: chromatin; nucleus
Genetic constraint (gnomAD): Loss-of-function variants: 0 observed, 10.07 expected, observed/expected ratio (o/e) 0, 90% interval 0 to 0.3. The synonymous counts are far from expectation, so gnomAD's model fits this gene poorly and the ratio says little. Missense variants: 40 observed, 224.31 expected, observed/expected ratio (o/e) 0.18, 90% interval 0.14 to 0.23. Synonymous variants: 21 observed, 98.57 expected, observed/expected ratio (o/e) 0.21, 90% interval 0.15 to 0.31.
Homologues: Orthologues: mouse Foxd4 (50% identical). Paralogues in human: FOXD4L6 (99% identical), FOXD4L4 (97% identical), FOXD4L5 (97% identical), FOXD4 (85% identical), FOXD4L1 (71% identical), FOXD1 (33% identical), FOXD2 (30% identical), FOXD3 (29% identical), FOXE3 (25% identical), FOXC1 (23% identical), FOXC2 (23% identical), FOXE1 (23% identical), and 29 more.